RBP4 (retinol binding protein 4)
Diseases named in the same sentence as RBP4 in open-access papers (continued):
Sharing a sentence is not in itself a finding about the gene and the disease.
tumor (continued). "In conclusion, our results suggested that RBP4-overexpression in tumor tissues is correlated with poorer prognosis of GBM patients." (PMID 36632438, 2022). "The tumor-related effects of RBP4 in GBM were finally evaluated by proliferation and invasion assays." (PMID 36632438, 2022). "ET-1 level in plasma and tumor tissue was significantly higher in mice bearing 67NR/RBP4 or 4T1/RBP4 cells than in appropriate controls." (PMID 32156052, 2020). "The level of VEGF in tumor tissue increased significantly, but only in mice bearing 67NR/RBP4 cells." (PMID 32156052, 2020). "Lung weight of mice bearing 67NR/RBP4 cells did not change as compared to that of controls; however, histopathological analysis revealed the presence of tumor cells in the lung tissue of 3/9 mice bearing 67NR/RBP4 cells." (PMID 32156052, 2020). "To delineate the contributions of serum versus autocrine secretion of RBP4 in the tumor microenvironment, we measured serum levels of RBP4 in a subset of patients from the KRAS wild-type and mutant groups." (PMID 28689994, 2017). "MYC and VEGFA levels were also increased in metastatic colon cancer cohort compared with primary tumor, similar to RBP4." (PMID 28689994, 2017). "Furthermore, RBP4-driven endothelial activation enhances vascular permeability and angiogenesis, contributing to tumor growth and dissemination." (PMID 41007818, 2025). "Because RBP4 is secreted by adipocytes, more adipose tissue results in overexpression of RBP4, and this may affect tumor progression." (PMID 41007818, 2025). "However, in colon and stomach tissue samples, normal tissues exhibited weaker RBP4 staining compared to tumor tissues." (PMID 40004479, 2025). "Additionally, RBP4 expression was observed in macrophages present within the tumor microenvironment." (PMID 41007818, 2025). "Moreover, cells treated with siRBP4-2# showed a statistically significant increase in migration, indicating that RBP4 knockdown enhances tumor cell migration." (PMID 40004479, 2025). "Functional assays indicated that RBP4 knockdown promoted tumor cell migration and proliferation." (PMID 40004479, 2025). "The enrichment analysis suggests that RBP4 may influence tumor cell biology through metabolism-related mechanisms." (PMID 40004479, 2025). "Abdominal fat, liver, tumor tissue, and plasma all showed elevated RBP4 levels." (PMID 39434876, 2024). "Intriguingly, RBP4+ tumor cells were highly enriched with hypoxia process." (PMID 38913193, 2024). "RBP4+ tumor cells were enriched in hypoxia processes and intensive cell-to-cell communication." (PMID 38913193, 2024). "In addition, 33 survival-related genes were observed to be elevated in tumor tissues, whereas 4 genes (RBP4, ABCB1, SCNA, and MAPT) showed increased expression in normal tissues." (PMID 35873484, 2022). "According to the migration and invasion tests, our data also revealed a similar conclusion on the potential metastasis-promoting effect of RBP4 in GBM, highlighting that RBP4 may become new therapeutic targets for both tumor growth and metastasis." (PMID 36632438, 2022). "Here, we also conducted cellular experiments to validate the tumor-related role of RBP4 in GBM." (PMID 36632438, 2022). "Besides the expression levels, online data mining revealed that the methylation of RBP4 in tumor tissues was positively correlated the overall survival of GBM patients (P=0.025)." (PMID 36632438, 2022). "RBP4 overexpression in tumor tissues is correlated with poorer prognosis of GBM patients, which functions by promoting GBM proliferation and invasion, thus, may serve as an invaluable predictive biomarker and therapeutic target." (PMID 36632438, 2022). "However, RBP4 expression was increased in tumor tissues in STAD, and the differences were statistically significant." (PMID 33834191, 2021). "The results suggest that RBP4 expression may inhibit tumor progression and serve as an indicator of better prognoses." (PMID 33834191, 2021).
tumor (continued). "The level of RBP4 protein was elevated in the tumor tissue of young and aged 4T1 tumor-bearing mice as compared to that in 67NR tumor-bearing mice and in the liver tissue of 4T1 tumor-bearing mice as compared to that of control healthy mice." (PMID 32156052, 2020). "Plasma level of RBP4 protein significantly increased in young and aged 4T1 tumor-bearing mice starting from approximately 2 weeks after cell transplantation and was significantly higher than that in 67NR tumor-bearing mice." (PMID 32156052, 2020). "Increased levels of RBP4 were observed in plasma, tumor tissue, liver, and abdominal fat." (PMID 32156052, 2020). "In addition, we observe a higher level of RBP4 in tumor, liver, and adipose tissue (young and old mice), and mammary glands (old mice) of 4T1-bearing mice when compared to 67NR." (PMID 32156052, 2020). "Moreover, we observed the impairment of tumor tissue angiogenesis (increased blood vessel permeability and decreased blood flow) when mice were transplanted with 67NR/RBP4 tumors or to a lesser extent even with transplantation of 4T1/RBP4 cells." (PMID 32156052, 2020). "Only tumors growing from 67NR/0 cells exhibited slow growth kinetics; therefore, the analyses of plasma and tissues and angiogenesis assessment were performed 10 days later, when tumor volumes of 67NR/0 tumors were comparable to those of wild-type and 67NR/RBP4 tumors." (PMID 32156052, 2020). "Moreover, increased ET-1 levels were observed in our studies at later steps of tumor progression (24–33 days), i.e., after a significant increase of RBP4 plasma level (day 12)." (PMID 32156052, 2020). "Downregulating STRA6 or RBP4 reduced the tumor-initiating cell frequency by ∼4.5-fold." (PMID 28689994, 2017). "Decreasing RBP4 levels slowed the kinetics of tumor progression." (PMID 28689994, 2017). "Moreover, our study underscores the broad relevance of RBP4 in tumor biology." (PMID 40004479, 2025). "In addition, a study indicates that RBP4 and NF-κB could function in tandem to enhance the tumor’s ability to propagate and metastasize." (PMID 39434876, 2024). "However, the fact that RBP4 is altered in several tumor types is contradictory." (PMID 36632438, 2022). "Therefore, both RBP4 and NF-κB may lead to a synergistic increase in the tumor progression and metastasis process observed in our studies." (PMID 32156052, 2020). "We employed survival analysis using the Kaplan–Meier method and utilized single-cell RNA sequencing (scRNA-seq) to investigate the roles of RBP4 and RBP7 in the tumor microenvironment." (PMID 41301068, 2025). "RBP4+ and CCL26+ tumor cells demonstrated enrichment in nearly all pathways, indicating their prominence in multiple biological processes." (PMID 38913193, 2024). "Through two independent validation cohorts, we finally identified five fecal tumor immune-related proteins (CAT, LTF, MMP9, RBP4, and SERPINA3) as well as a biomarker panel that had definite diagnostic value for CRC." (PMID 37313408, 2023). "Conversely, levels of apelin, CCL2, progranulin, interleukin-6, chemerin, retinol binding protein 4 (RBP4), resistin, and plasminogen activator inhibitor-1 (PAI-1) expression were lower in tumor tissue than in adjacent normal tissue." (PMID 36917086, 2023). "In the present study, we performed bioinformatic analyses to explore any relationships between RBP4 expression and HCC patient survival using data from tumor and normal tissue samples." (PMID 33834191, 2021). "Studies have also demonstrated that RBP4 activates STRA6, which drives and mediates tumor initiation, tumor growth, and the expression of stemness markers in the genesis of colon cancer." (PMID 33834191, 2021). "On the contrary, RBP4 and MIOX were highly expressed in tumour cells 1 from ccRCC2, and ANXA1 and MUC20-OT1 were highly expressed in tumour cells 2 from ccRCC2 but lowly expressed in tumour cells 2 from ccRCC1." (PMID 34168986, 2021).
tumor (continued). "Among them, four genes, including APOL1, CCL17, RBP4, and KRT71 were selected in real-time PCR experiments between tumor samples and normal samples, which were found to be consistent with the expression trend in low- and high-risk groups." (PMID 33335850, 2020). "Expression for MMP3 (t = 4.884, p < 0.0001), SLC2A1 (t = 3.703, p = 0.0006), DDK3 (t = 3.981, p = 0.0003), POSTN (t = 2.061, p = 0.0455), RBP4 (t = 3.048, p = 0.004) and ASPN (t = 2.733, p = 0.0091) was confirmed to be higher in the tumor tissues." (PMID 32854182, 2020). "Two proteins higher in the tumor patients, as compared to healthy volunteers, resulted in additional increase after the infusion of BPA: Retinol-binding protein 4 (RBP4) and Protein AMBP (AMBP)." (PMID 30813269, 2019). "To assess the role of RBP4 in tumor progression, we subcutaneously injected the SW480 line, in which RBP4 was stably downregulated using shRNA, into athymic nude mice." (PMID 28689994, 2017). "Then, the serum RBP4 and THBS2 concentrations were graded according to the 7th edition of the International Union against Cancer (UICC) tumor node metastasis (TNM)." (PMID 29190912, 2017). "Immunohistochemistry (IHC) study was performed on type I EC tumor samples using five adipokines (SPARC, RBP4 (Retinol Binding Protein 4), adiponectin, TNF α, IL-6) and hormonal receptors (estrogen receptor and progesterone receptor)." (PMID 28505082, 2017). "RBP4 knockdown caused a more than 3-fold reduction in tumor volume and significantly attenuated tumor initiation as indicated by the formation of only two tumors out of eight injected animals, unlike the control in which every injection resulted in tumor formation." (PMID 28689994, 2017). "A candidate‐based screen of tumor lysates and differential protein arrays of cultured HSC identified several established hepatotropic cytokines, including IGF2, RBP4, DKK1, and CCL5 as being negatively regulated by endosialin." (PMID 28373218, 2017). "On the other hand, the expression of RBP4 and PLAC8 was increased in tumor cells from mice injected with PC3-GFP/PC3-OPG in accordance with the results from RT-PCR and cDNA microarray analysis." (PMID 23708710, 2013). "Mechanistically, RBP4 can activate macrophages via exosomal signaling, trigger STRA6-mediated Janus kinase (JAK)/STAT3/STAT5 activation, and promote pro-inflammatory responses that support tumor progression, migration, and metastasis." (PMID 41007818, 2025). "The study revealed that RBP4 expression levels were higher in tumor tissues compared to adjacent non-cancerous tissues." (PMID 41007818, 2025). "Unfortunately, we did not detect differential protein expression of RDM1 and RBP4 between normal oral and tumor tissues." (PMID 37647077, 2023). "Additionally, we assessed the tumor-related function of RBP4 in GBM cell lines by testing their proliferation, migration, and invasion after RBP4 interference." (PMID 36632438, 2022). "Although the plasma level of RBP4 was also increased in 67NR tumor-bearing mice, the increase was not significant in young mice and was significant in aged mice only on the last day of observation (respectively)." (PMID 32156052, 2020). "The potential role of NF-κB signaling in the mechanism of the effects of RBP4 observed in our studies may be supported by the observation that NF-κB regulates the expression of VEGF (and thus tumor angiogenesis)." (PMID 32156052, 2020). "The overexpression of RBP4 increased the level of VEGF in the tumor tissue of 67NR/RBP4, but not in the cell culture of these cells." (PMID 32156052, 2020). "In silico analyses confirmed the transcriptional upregulation of IL6 and RBP4 in CRC and revealed distinct molecular pathways—immune/inflammatory signaling for IL-6 and developmental signaling for RBP4—highlighting their possible contributions to tumor biology." (PMID 41007818, 2025).
tumor (continued). "The RBP4 protein level was significantly increased in plasma, tumor tissue, and liver of mice bearing 67NR/RBP4 or 4T1/RBP4 cells as compared to that in mice inoculated with cells not overexpressing RBP4." (PMID 32156052, 2020). "Therefore, we analyzed the phosphorylation status of STAT3 in tumor tissue and cell culture and found that it did not change with the overexpression of RBP4." (PMID 32156052, 2020). "We also assessed the effect of RBP4 overexpression on STAT3 phosphorylation in 67NR/RBP4 cells in vitro (as well as in 67NR/RBP4 and 4T1/RBP4 tumor cell lysates), and we did not observed significant differences between wild-type or empty vector-transduced cell lines and Rbp4-transduced cells." (PMID 32156052, 2020). "IHC analysis on type 1 EC showed that the selected adipokines are differently expressed within the tumor; staining could be located in the cytoplasm of EC cells (TNF α and RBP4), in the cytoplasm of stromal cells (adiponectin) or both in EC and stromal cells (IL-6 and SPARC)." (PMID 28505082, 2017). "The effect of RBP4 on tumor growth has not been studied, and whether this pathway affects tumor initiation is unknown." (PMID 28689994, 2017). "Interestingly, tumors overexpressing RBP4 led to increased (as compared to that in wild-type or transduced with control vector cell lines) level of RBP4 only in the liver (besides tumor tissue and plasma) and not in the mammary gland or abdominal adipose tissue." (PMID 32156052, 2020).
kidney disease (23 papers, 2010 to 2025). "Parathyroid hormone-related protein (PTHrP) and retinol-binding protein 4 (RBP4) have been associated with a worse prognosis of kidney disease." (PMID 39795999, 2024). "Multiple RBP4 variants were identified previously, including the loss of one or two C-terminal leucine residues that are involved in kidney disease." (PMID 39521382, 2024). "Here, we summarize the most important existing data on the associations between urinary retinol-binding protein 4 and renal diseases and highlight the untapped potential of retinol-binding protein 4 in clinical use." (PMID 36011513, 2022). "Creatinine levels further suggested that the rats were free of underlying renal disease that might influence RBP4 levels." (PMID 34417282, 2021). "Further studies should be carried out to examine the association between RBP4 and kidney disease." (PMID 30135138, 2018). "Renal function also affects circulating RBP4 and can be assessed by plasma creatinine levels, where high levels are indicative of kidney disease." (PMID 34417282, 2021). "This meta-analysis is the first to present the role of circulating RBP4 in kidney diseases in subjects with T2DM." (PMID 33082885, 2020). "To explore the relationship between circulating RBP4 concentration and kidney diseases, we performed a correlation analysis between RBP4 and eGFR/ACR." (PMID 33082885, 2020). "Serum RBP4 level is often used as a clinical indicator of kidney disease for early diagnosis and curative effect evaluation." (PMID 29190912, 2017). "Therefore, RBP4 is often used as a clinical indicator for early diagnosis and efficacy evaluation of renal diseases." (PMID 34889069, 2022). "The discovery of RBP4 in human urine by Kanai in the late 1960s initiated “an avalanche” of research into it in the context of its characteristics, as well as its applicability as a renal disease biomarker." (PMID 36011513, 2022). "In addition, we found that several DEPs such as RBP4 and GDF15are related to various renal diseases." (PMID 34669736, 2021). "However, our study provides some insights regarding RBP4 role on IR in a different setting characterized by severe kidney disease requiring hemodialysis." (PMID 29333450, 2017). "However, in renal diseases, RBP4 levels in urine increase, indicating tubular damage." (PMID 39795999, 2024). "Moreover, RBP4 levels have been reported to be elevated in kidney disorders in late stages." (PMID 33574979, 2021). "Circulating RBP4 could be a reliable biomarker for kidney diseases in T2DM." (PMID 33082885, 2020). "There may be two reasons to explain these differences in circulating RBP4 levels in diabetic subjects with and without kidney diseases." (PMID 33082885, 2020). "Thus, disorder of renal function leads to accumulation of RBP4 in the plasma and hence to higher concentration in patients with DN than in T2DM patients without kidney disease." (PMID 38711978, 2024). "Similarly, circulating RBP4 levels in subjects with T2DM and advanced kidney diseases were significantly higher than those in patients without kidney diseases." (PMID 33082885, 2020).
infection (11 papers, 2017 to 2026). The state of being infected such as from the introduction of a foreign agent such as serum, vaccine, antigenic substance or organism. "Overexpression of RBP4 promotes IAV infection while its deficiency suppresses infection by the human influenza virus H1N1, swine influenza virus H3N2, and avian influenza virus H9N2, both in vitro and in vivo." (PMID 41144502, 2025). "In addition, the expression of pro-inflammatory cytokines, such as Il1b, Tnf and Il6, was also reduced in RBP4-deficient mice on day 3 post-infection, indicating a decrease inflammation." (PMID 41144502, 2025). "Additionally, immunofluorescence staining for NP, predominantly localized to the nuclei during the early stage of infection, revealed that RBP4 deficiency significantly reduced the number of fluorescent nuclei." (PMID 41144502, 2025). "We then intranasally infected WT and RBP4-deficient mice with WSN for 3 days to test virus replication, monitored disease progression, and recorded body weight changes for 6 days of infection." (PMID 41144502, 2025). "qPCR analysis in HEK293T cells infected with WSN showed significant RBP4 induction as early as 6 hours post-infection, implying that virus replication is likely dispensable for this response." (PMID 41144502, 2025). "In the present study, more than one-third of the patients had insufficient RBP4 concentration even though the time elapsed, at the time of evaluation, had already passed the acute phase of infection." (PMID 38541764, 2024). "In contrast to reduction in RBP4 during infection, alternate acute-phase proteins called serum amyloid A (SAA1 and 2) that bind retinol with high affinity are strongly up-regulated in the intestinal as well as liver tissues." (PMID 31170262, 2019). "For HPX, CP and RBP4 differential abundance was observed only in the FEB stage of the infection, while alterations in their serum abundances during the DEF and CON stages were found to be statistically insignificant (p > 0.05)." (PMID 28667326, 2017). "Moreover, RBP4 expression is induced in vitro or in vivo in response to infection by several RNA viruses, including human immunodeficiency virus and IAV." (PMID 41144502, 2025). "Furthermore, RBP4 expression is also correlated with infection by certain viruses." (PMID 41144502, 2025). "Hence, RBP4 levels appear to modulate IAV-driven pathogenesis, and suppression of RBP4 could attenuate IAV replication or infection." (PMID 41144502, 2025). "In vitro, HCV stimulates RBP4 expression, while RBP4 knockdown increases HCV replication, suggesting that RBP4 upregulation may be a mechanism of viral attenuation or an adaptive host response to infection." (PMID 31170218, 2019). "Notably, RBP4 levels are significantly increased in hospitalized patients diagnosed with influenza A (H1N1) pdm09 virus infection, correlating with clinical severity of the infection." (PMID 41144502, 2025). "At the site of infection, expression of genes regulating vitamin A transport and metabolism (STRA6, RXRα, RBP4) increased (P ≤ 0.002) in non-lesion lung relative to diseased lung." (PMID 41476140, 2026).